RNU6-83P (RNA, U6 small nuclear 83, pseudogene)
Synonyms: RNU6-83
Gene: Small nuclear RNA gene on chromosome 13 (99,025,234 to 99,025,345, forward strand). Ensembl gene ENSG00000207298.
Homologues: Orthologues: macaque U6 (88% identical), mouse Gm25337 (83% identical), mouse Gm22229 (80% identical). Paralogues in human: RNU6-1209P (85% identical), RNU6-188P (85% identical), RNU6-560P (85% identical), RNU6-742P (85% identical), RNU6-86P (85% identical), RNU6-116P (84% identical), RNU6-1175P (84% identical), RNU6-11P (84% identical), RNU6-266P (84% identical), RNU6-37P (84% identical), RNU6-698P (84% identical), RNU6-744P (84% identical), and 1287 more.